ISM1 (isthmin 1)
Diseases named in the same sentence as ISM1 in open-access papers (continued):
Sharing a sentence is not in itself a finding about the gene and the disease.
bacterial infection (2 papers, 2022 to 2025). "Finally, ISM1 luminal levels were slightly increased, suggesting a role for ISM1 during bacterial infection." (PMID 40572169, 2025). "Finally, bacterial infection increased both LSK and ISM1+LSK cell numbers, most likely through activation of TLRs." (PMID 35402623, 2022). "Furthermore, when we analyzed the ISM1+LSK subset (Lin− CD45+ ISM1+ c-kit+ Sca-1+), we found that the absolute numbers of ISM1+LSK cells were significantly increased, indicating that ISM1+-HSC cells are also altered during bacterial infection." (PMID 35402623, 2022).
cardiac disease (1 paper, 2024). "ISM1 may serve as a novel potential therapeutic target for preventing aging-related cardiac disease in elderly populations." (PMID 38300636, 2024). "ISM1 prevents aging-related cardiac dysfunction by promoting glycolysis and enhancing SIRT1 deacetylase activity, making it a promising therapeutic target for aging-related cardiac disease." (PMID 38300636, 2024).
epithelial carcinoma (1 paper, 2023). "TNF-α/NF-κB and IL-6/JAK/STAT3 are common markers of Epstein–Barr virus-associated epithelial carcinoma, and ISM1 affects both pathways." (PMID 36995541, 2023).
inflammation (1 paper, 2022). Aberrant reaction of the microcirculation characterized by movement of fluid and leukocytes from the blood into extravascular tissues. "In this study, we investigated how ISM1 influences LPS-induced acute pulmonary inflammation using Ism1−/− mice and intranasal instillation of recombinant ISM1 (rISM1)." (PMID 35752760, 2022). "Moreover, intranasal delivered recombinant ISM1 (rISM1) effectively suppressed LPS-induced acute lung inflammation and ALI, and rISM1 suppressed LPS-induced NF-κB activation in cultured mouse alveolar macrophages." (PMID 35752760, 2022). "Hence, lung resident ISM1 inhibit LPS-induced acute lung inflammation by inhibiting LPS-induced NF-κB activation as well as the production of multiple proinflammatory cytokines." (PMID 35752760, 2022).
psychiatric disorder (1 paper, 2023). A disorder characterized by behavioral and/or psychological abnormalities, often accompanied by physical symptoms. "The gene ISM1 (Isthmin 1) located on chromosome 20 has not been previously linked to psychiatric disorders or ASD." (PMID 37891789, 2023).
renal disease (1 paper, 2023). "The present study aims to elucidate whether ISM1 is involved in the mechanisms leading to glomerular damage during renal disease progression particularly focused on podocytes." (PMID 36769045, 2023).
ISM1 also shares sentences with these, for which no sentence is quoted: breast carcinoma (1 paper); cholangiocarcinoma (1); chronic obstructive pulmonary disease (1); esophageal carcinoma (1); hyperlipidemia (1); Infertility (1); inflammatory bowel disease (1); intestinal cancer (1); intestinal diseases (1); Kabuki syndrome (1); lung injury (1); Nephropathy (1); pancreatic adenocarcinoma (1); pancreatic cancer (1); rectal adenocarcinoma (1); Salmonella Infections (1); spinal cord disease (1); stomach adenocarcinoma (1).